RNF125 (ring finger protein 125)
Description:
Acts as a negative regulator of type I interferon production by mediating ubiquitination of RIGI at 'Lys-181', leading to RIGI degradation. Mediates ubiquitination and subsequent degradation of JAK1. Acts as a positive regulator of T-cell activation.
Synonyms: TRAC-1; FLJ20456; TNORS; TRAC1
Tractability: PROTAC: UniProt records ubiquitination sites on it; ubiquitination databases record sites on it.
Gene: Protein-coding gene on chromosome 18 (32,018,174 to 32,088,144, forward strand). Ensembl gene ENSG00000101695.
Subcellular location: Golgi apparatus membrane
Subcellular location (Human Protein Atlas): Golgi apparatus; Nucleoli
Pathways (Reactome):
Immune System: Negative regulators of DDX58/IFIH1 signaling
Gene Ontology:
Molecular function: protein binding; ubiquitin conjugating enzyme binding; ubiquitin protein ligase activity; zinc ion binding; ubiquitin-protein transferase activity
Biological process: negative regulation of RIG-I signaling pathway; negative regulation of type I interferon production; protein polyubiquitination; ubiquitin-dependent protein catabolic process; protein ubiquitination
Cellular component: Golgi apparatus; Golgi membrane; intracellular membrane-bounded organelle; VCP-NPL4-UFD1 AAA ATPase complex; cytoplasm
Genetic constraint (gnomAD): Loss-of-function variants: 4 observed, 8.54 expected, observed/expected ratio (o/e) 0.47, 90% interval 0.23 to 1.07. That is too few expected variants to judge how well the gene tolerates losing a copy. Missense variants: 141 observed, 149.58 expected, observed/expected ratio (o/e) 0.94, 90% interval 0.82 to 1.08. Synonymous variants: 55 observed, 59.03 expected, observed/expected ratio (o/e) 0.93, 90% interval 0.75 to 1.17.
Homologues: Orthologues: chimpanzee RNF125 (99% identical), macaque RNF125 (97% identical), dog RNF125 (91% identical), mouse Rnf125 (86% identical), rat Rnf125 (86% identical), guinea pig RNF125 (82% identical), pig RNF125 (81% identical), tropical clawed frog rnf125 (43% identical). Paralogues in human: RNF166 (31% identical), RNF138 (29% identical), RNF114 (28% identical), RNF180 (18% identical).
Diseases named in the same sentence as RNF125 in open-access papers:
RNF125 is named in the same sentence as 32 diseases in open-access papers, as found by Europe PMC text mining. Sharing a sentence is not in itself a finding about the gene and the disease. The quoted sentences say what the papers report.
viral infection (6 papers, 2012 to 2022). "G3BP1 potentiates the RIG-I-related pathway via RNF125-mediated K48-linked polyubiquitination in response to viral infection, which results in IRF3 phosphorylation and increased IFN-β transcription." (PMID 35652658, 2022). "In addition to K63-ubiquitination at MAVS K500, MAVS can link K48-polyubiquitin chains following virus infection and is the target for proteasomal degradation by the E3 ligase RNF125, suggesting that MAVS may undergo multiple ubiquitination events." (PMID 22844514, 2012). "Collectively, these results demonstrated that RNF125 is as a tumor suppressor in mouse and human livers, regardless of the viral infection status, which is consistent with our transposon screening results." (PMID 35681566, 2022). "MEX3C, TRIM4 and TRIM25 are the most important E3 ligases for positive regulation of RIG-I activity in response to viral infection, whereas RNF122 and RNF125 have been described to mediate the ubiquitin-dependent degradation of this cytosolic innate immune receptor." (PMID 32019099, 2020).
melanoma (5 papers, 2017 to 2025). A malignant, usually aggressive tumor composed of atypical, neoplastic melanocytes. "Targeting JAK1 and EGFR signaling successfully overcame BRAFi resistance in melanomas with low RNF125 expression, both in vitro and in in vivo xenograft models." (PMID 40872623, 2025). "Another mechanism contributing to acquired resistance is the decreased RNF125 protein expression in resistant melanoma cells." (PMID 40872623, 2025). "Consistent with our findings, even in Kim’s study, RNF125 knockdown seemed to increase cell growth under low levels of BRAFi treatment (10−10 to 10−9 M), while RNF125 overexpression decreased growth in the UACC1113 melanoma cell line." (PMID 35681566, 2022). "A decreased level of RNF125 transcript in BRAFi-resistant melanoma cells conferred a growth advantage in the presence of BRAFi." (PMID 33800394, 2021). "For example, downregulation of the ubiquitin ligase RNF125 was shown to be involved in intrinsic and adaptive resistance to BRAFi in melanomas through the inhibition of JAK/STAT signaling." (PMID 32346533, 2020). "Using the BRAFi-resistant cell line, they found increased cell growth upon RNF125 depletion in the presence of BRAFi, but decreased cell growth with RNF125-overexpression, demonstrating that RNF125 is involved in the development of BRAFi-resistance in melanoma." (PMID 35681566, 2022). "RNF125, as a little studied E3 ubiquitin-protein ligase, was recently reported to play a promoting role in lymph node metastasis of colorectal cancer; its expression downregulation was correlated with resistance of melanoma cells to BRAF inhibitors." (PMID 28611292, 2017). "In melanoma cell cultures and tumor samples, SOX10/MITF expression was found to correlate with and drive RNF125 transcription." (PMID 40872623, 2025). "The inhibition of Janus kinase 1 (JAK1) activity due to ubiquitination by RNF125 decreased EGFR expression at the transcriptomic and protein levels, overcoming BRAFi resistance in melanoma cells." (PMID 33800394, 2021).
Tenorio syndrome (4 papers, 2020 to 2024). "These include the Tenorio syndrome caused by RNF125 deficiency which, beside syndromic intellectual disability, leads to a severe inflammatory phenotype with recurrent episodes of conjunctivitis and stomatitis." (PMID 34566579, 2021). "RNF125 is associated with Tenorio syndrome (OMIM 616260), an autosomal dominant disease characterized by overgrowth, macrocephaly, and intellectual disability." (PMID 33584815, 2020). "Pathogenic variants in RNF125 putatively influence the MAPK–pathways with an yet unclear mechanism and cause the Tenorio syndrome (TNORS)." (PMID 38894719, 2024). "The immune manifestations of the Tenorio syndrome clearly corroborate the fact that RNF125 acts as a negative regulator of innate immune signaling by targeting key pattern recognition receptors (i.e., RIG-1, MDA5) for degradation." (PMID 34566579, 2021).
Sepsis (3 papers, 2021 to 2025). Sepsis is defined as life-threatening organ dysfunction caused by a dysregulated host response to infection. "Three shared key genes (HCK, NOG, RNF125) were obtained, that have a good diagnostic value for both sepsis and ALL." (PMID 38123749, 2025). "Our study gives a comprehensive analysis, involving the common gene signatures of HCK, NOG, and RNF125 in pediatric acute lymphoblastic leukaemia and pediatric sepsis, together with related biological mechanism." (PMID 38123749, 2025). "Previous bioinformatics analyses of pediatric ALL and pediatric sepsis cases have revealed three shared key genes (ring finger protein 125 (RNF125), noggin (NOG), and hemopoietic cell kinase (HCK))." (PMID 41007866, 2025). "In summary, this study is the first to analyze pediatric ALL and pediatric sepsis through bioinformatics, and three shared key genes (RNF125, NOG, and HCK) have been obtained." (PMID 38123749, 2025). "Phosphorylation of serine 5 in the PYD inhibits the activation of NLRP3.Sequential ubiquitination of NLRP3 by RNF125 and Cbl-b inhibits the activation of NLRP3 and prevents the development of sepsis in mice." (PMID 34745104, 2021). "On that account, RNF125 can positively help to inhibit ALL and pediatric sepsis." (PMID 38123749, 2025).
gallbladder cancer (2 papers, 2017 to 2022). "RNF125 was found to promote invasion and metastasis of gallbladder cancer via the TGF-β1-SMAD3-ID1 pathway and was associated with worse outcomes." (PMID 35568845, 2022).
head and neck squamous cell carcinoma (2 papers, 2023 to 2024). A squamous cell carcinoma that arises from any of the following anatomic sites: lip and oral cavity, nasal cavity, paranasal sinuses, pharynx, larynx, and salivary glands. "RNF125 suppresses immune escape in head and neck squamous cell carcinoma." (PMID 38638430, 2024). "RNF125 E3 ligase suppresses tumorigenesis and growth in vivo and inhibits immune escape in head and neck squamous cell carcinoma (HNSCC)." (PMID 37296972, 2023). "In head and neck squamous cell carcinoma (HNSCC) cells, RNF125 expression was low." (PMID 38638430, 2024).
liver cancer (2 papers, 2022 to 2024). An epithelial or non-epithelial malignant neoplasm that arises from the liver. "Since the importance of GH signaling in liver cancer development and its clinical impact have been already reported, we decided to focus on functional analysis of RNF125." (PMID 35681566, 2022). "Depletion of RNF125 in immortalized mouse liver cells led to tumor formation in transplanted mice and accelerated growth of human liver cancer cell lines, while its overexpression inhibited their growth, demonstrating the tumor-suppressive function of RNF125 in mouse and human liver." (PMID 35681566, 2022). "None of the liver cancer cell lines used in these studies had mutations in RNF125." (PMID 35681566, 2022). "Previous studies showed that parkin RBR E3 ubiquitin‐protein ligase (PARK2) and ring finger protein 125 (RNF125) can regulate Srsf1 ubiquitination in human lung cancer and liver cancer cells." (PMID 38520084, 2024).
lung adenocarcinoma (2 papers, 2022 to 2024). A carcinoma that arises from the lung and is characterized by the presence of malignant glandular epithelial cells. "In the two-sample Mendelian randomization (MR) analysis, it was observed that RNF125, CD8B, and TRGV9 exhibit no heterogeneity concerning lung adenocarcinoma (LUAD)." (PMID 38297377, 2024).
lung carcinoma (2 papers, 2024). "The results showed a significant association of RNF125 mutations with lung cancer risk (OR = 0.5858, 95% CI: 0.3504–0.9793)." (PMID 38297377, 2024). "We explored the association between three genes, namely RNF125, CD8B, and TRGV9, and lung cancer risk." (PMID 38297377, 2024).
overgrowth syndrome (2 papers, 2016 to 2022). A group of syndromes caused by genetic birth defects that may lead to the development of malignancies. "Recently, mutations in RNF125 have been associated with a new overgrowth syndrome, characterized by macrocephaly as well as inflammatory disease." (PMID 27411375, 2016). "Thus, M112 was mutated to an Ala, and to an Ile to generate the RNF125 mutant detected in some of the overgrowth syndrome patients." (PMID 27411375, 2016).
myeloma (1 paper, 2024). "The results suggest that three genes, CRIP1, HIST1H1C and RNF125, are significantly overexpressed in myeloma cell lines and may contribute to the poor prognosis in malignant plasma cell samples, whereas C1orf56 and S100A6 may contribute to the poor prognosis in microenvironmental cell samples." (PMID 38278930, 2024).
oral squamous cell carcinoma (1 paper, 2024). "Ring finger protein 125 (RNF125) promotes ubiquitin-mediated degradation of PD-L1 and downregulates PD-L1 in oral squamous cell carcinoma (OSCC) TSCCA cells." (PMID 38654302, 2024).
infection (9 papers, 2016 to 2024). The state of being infected such as from the introduction of a foreign agent such as serum, vaccine, antigenic substance or organism. "We first confirmed that lentiviral infection of RNF125 shRNAs significantly downregulated RNF125 expression in both cell lines." (PMID 35681566, 2022). "Both 293T cell cotransfection and infection studies in PAM cells showed that ASFV MGF-505-7R interacted with RNF125." (PMID 34517008, 2021). "Most of these genes were up-regulated more rapidly and strongly in the HEP-Flury infection than the CVS-11 at 4 dpi besides RNF125." (PMID 27242764, 2016). "RNF125 is primarily expressed in lymphoid tissues and is a positive regulator of T lymphocyte activation, which may be critical for modulating inflammatory pathways and adaptive host defense against infection in desert tortoises." (PMID 32846428, 2020). "The genes ABHD8, CDO1, RNF125, cell surface hyaluronidase-like, and gopAga1_00017729 were upregulated in medium and severely infected animals relative to control, indicating these may be biomarkers of infection." (PMID 32846428, 2020). "For instance, RNF125, IFI35, NLRC5, USP25, and A20 have been shown to negatively regulate RIG-I-induced antiviral signaling upon pathogen infection." (PMID 33584728, 2020). "Taken together, upon infection with RNA viruses, G3BP1 increases ubiquitination of RNF125 to attenuate RNF125 expression, thereby promoting the expression of RIG-I." (PMID 31827077, 2019). "After 3 days of lentiviruses infection shRNA, the invasive cells per field of NOZ cells were significantly reduced following RNF125 knockdown (**P = 0.000); and, the adhesion rate of NOZ cells was significantly increased in shRNF125 as compared to shCtrl (#P = 0.022)." (PMID 28611292, 2017). "The RT-qPCR analysis revealed that the RIG-I, MDA5 and their regulators such as RING finger protein 125 (RNF125), Interferon-stimulated gene 15 (ISG15), DExH (Asp-Glu-X-His) box polypeptide 58 (Dhx58, also known as LGP2) were up-regulated following CVS-11 and HEP-Flury infections." (PMID 27242764, 2016). "As expected, we also observed that ASFV-Δ7R infection elevated the JAK1, JAK2, and Hes5 expression level in PAM cells, but not the RNF125 and ASFV p30 expression level in comparison with those of parental ASFV-infected cells." (PMID 34517008, 2021).
cancer (7 papers, 2021 to 2025). A tumor composed of atypical neoplastic, often pleomorphic cells that invade other tissues. "RNF125 expression is significantly downregulated in several cancers, including CCA, HCC and CRC, and is negatively correlated with the clinical stage, whereas higher expression is associated with better clinical outcomes." (PMID 39766812, 2024). "To verify the functional importance of RNF125 in cancer immune escape, we first constructed a PD-L1-overexpressing (PD-L1-OE) MC-38 cell line and implanted subcutaneously in C57BL/6N mice." (PMID 35965501, 2022). "Currently, accumulating studies have demonstrated that RING fingers (RNFs), such as RNF43, RNF20, RNF125, RNF6, and RNF183, are significantly associated with the development of cancers." (PMID 35568845, 2022). "Using Kaplan–Meier survival analysis curves, which divided the RNF125 into high and low expression groups according to cutoff values, we next assessed the relationships between RNF125 and the clinical outcome of cancer." (PMID 35965501, 2022). "Collectively, these findings manifest that compartment switching induced by Arid1a depletion modulates the transcription of some cancer-related genes, such as Pmp22, Atg10, Gsc, Rnf125, and Cdh5, which have been known to be involved in tumorigenesis." (PMID 34689165, 2021). "Additionally, RNF125 expression was found to be notably reduced in various human cancer tissues, inversely related to the clinical stage of the cancers, and tumor patients with elevated RNF125 levels displayed more favorable clinical outcomes." (PMID 38638430, 2024). "Our results showed that RNF125 was down-regulated in various cancers." (PMID 35965501, 2022). "Moreover, RNF125 expression was significantly downregulated in several human cancer tissues, and was negatively correlated with the clinical stage of these tumors, and patients with higher RNF125 expression had better clinical outcomes." (PMID 35965501, 2022). "Additionally, RNF125 expression was significantly down-regulated in multiple human cancer tissues, and patients with higher RNF125 expression had better clinical outcomes." (PMID 35965501, 2022). "We next tested whether overexpression of RNF125 exerts a tumor suppressive function in human cancer cell lines." (PMID 35681566, 2022). "Here we show that RNF125, a candidate cancer gene identified in liver-specific transposon screens performed in mice that carried or lacked a sensitizing HBs-Ag transgene, is a potent tumor suppressor gene in mouse and human HCC and functions as a negative regulator of cell proliferation." (PMID 35681566, 2022). "Hence, enhanced RNF125 expression or E3 ligase activity may exert tumor-suppressive effects in cancer cells." (PMID 35965501, 2022). "To investigate the potential clinical role of RNF125 in cancers, we then used ”UANCAN” website to analyze the expression of RNF125 in tumors and normal tissues." (PMID 35965501, 2022).